TWIST1 (twist family bHLH transcription factor 1)
Diseases named in the same sentence as TWIST1 in open-access papers (continued):
Sharing a sentence is not in itself a finding about the gene and the disease.
breast carcinoma (continued). "For examples, Twist1 recruits Mi2/NuRD complex including HDAC1 and HDAC2 to the E-cadherin and ERα promoters causing histone deacetylation and chromatin condensation, further reducing transcript levels, thus to promote EMT and metastasis of breast cancers." (PMID 28394356, 2017). "Interestingly, Twist1 silencing in breast cancer cells can be mediated by ID1 (inhibitor of differentiation 1) promoting a stem‐like phenotype while maintaining epithelial properties at distant sites." (PMID 28590039, 2017). "Similarly, Twist1 overexpression induces EMT in MCF-7 breast cancer cells, which can then form VM channels in 3D culture medium." (PMID 27034014, 2017). "The exact roles of CCND2 and TWIST1 in breast cancer are unresolved." (PMID 28222775, 2017). "Mitogen-activated protein kinase (MAPK) pathway is vital for Twist1 stability in breast cancer." (PMID 26959880, 2016). "Consistently, Twist1 has been shown to promote breast cancer metastasis to the lung." (PMID 27105506, 2016). "In addition, after infection with adenoviruses expressing miR-151, we found that the mRNA and protein expression levels of TWIST1 were significantly decreased in human breast cancer cells." (PMID 27930738, 2016). "The TWIST1 expression in breast cancers may be regulated by several mechanisms, including the transcription factors in response to EMT stimulators and miRNAs." (PMID 27930738, 2016). "TWIST1 is a highly conserved basic helix-loop-helix transcription factor that contributes to cancer metastasis by promoting an epithelial-mesenchymal transition and repressing E-cadherin gene expression in breast cancer." (PMID 27930738, 2016). "It is possible that the increased miR-151-3p in breast cancers could be partly involved in the regulation of TWIST1 gene expression at different stages of cancer progression." (PMID 27930738, 2016). "Several studies have suggested that Twist1 is associated with pathways in the EMT process such as Wnt/β-catenin signaling, PI3K/AKT/TGF-β signaling, AKT2 signaling, and NF-κB signaling in breast cancer cells." (PMID 27494849, 2016). "In human breast cancers, TWIST1 is usually found to be over-expressed, which is correlated with invasive lobular carcinoma, a highly infiltrating tumor type associated with loss of E-cadherin expression, lymph-node and distant metastases, and poor patient prognosis." (PMID 27930738, 2016). "In human breast cancer, the analysis of TWIST1 expression has shown to be variable." (PMID 29056725, 2016). "Given the requirement for E-cadherin in Twist1+ single-cell dissemination and in breast cancer metastasis to bone, we speculate that intercellular junctions have an underappreciated role in cancer progression." (PMID 27402962, 2016). "In conclusion, our results suggested that TWIST1 is the direct target of miR-151-3p and that miR-151-3p may play a negative regulatory role in breast cancer metastasis." (PMID 27930738, 2016). "Correlations of microRNAs and TWIST1 gene expression in human breast cancers." (PMID 27930738, 2016). "To ascertain whether miR-129-5p regulates breast cancer progression through its interaction with Twist1, we performed a rescue experiment." (PMID 26460733, 2015). "Tumor expression of TWIST1 and SLUG are associated with poor outcome in breast cancer patients; therefore, we decided to correlate presence of CTCs in peripheral blood with expression of TWIST1 and SLUG in breast cancer cells and cancer associated stroma." (PMID 26194471, 2015). "Given that BRMS1 inhibits Snail and TWIST1 expression and that hypoxic condition induces Snail and TWIST1 expression in breast cancer cells, we hypothesized that BRMS1 inhibits HIF-1α expression." (PMID 26520789, 2015). "Moreover, there is a significant inverse correlation between miR-129-5p and Twist1 expression levels in breast cancer tissues, suggesting a functional interaction of miR-129-5p and Twist1." (PMID 26460733, 2015).
breast carcinoma (continued). "miR-129-5p suppressed EMT in human breast cancer by directly targeting Twist1." (PMID 26460733, 2015). "In addition, AKT directly phosphorylates TWIST1 at Ser42 to promote TWIST1-mediated expression of TGFβ2, leading to enhanced TGFβ signaling in breast cancer cells." (PMID 26204939, 2015). "In addition, miRNA can act pleiotropically; therefore, HMGA2, SALL4 and Twist1 are the ideal targets of miR-33b in modulating the stemness of breast cancer cells." (PMID 25919570, 2015). "This indicates that TWIST1 knockdown reduced metastasis in breast cancer model of mouse." (PMID 26023736, 2015). "Since hypoxia increased Snail and TWIST1 expression, we next determined whether HIF-1α is implicated in TGF-β1-induced Snail and TWIST1expression in breast cancer cells." (PMID 26520789, 2015). "In this study, TWIST1 gene was knocked down in 4T1 mouse breast cancer cells by shRNA technology." (PMID 26023736, 2015). "In the current study, we investigated whether anti-TWIST1 siRNA could be functionally delivered to metastatic breast cancer cells (SUM 1315 cell line) using YTZ3-15." (PMID 25759817, 2015). "The miR-720 could suppress cell migration and invasion in breast cancer by directly targeting TWIST1." (PMID 26413265, 2015). "Since our data indicated that WAVE2 loss led to a coordinated decrease in E-cadherin and increase in N-Cadherin mRNA levels, we analyzed the expression of three EMT-associated transcription factors known to drive cadherin switching in breast cancer cell lines, Slug, Snail and Twist1." (PMID 23691243, 2013). "In breast cancer (BC), Twist1 has been found to promote EMT and invasiveness." (PMID 23815808, 2013). "Furthermore, TWIST1 mediated angiogenesis in mammary carcinoma in clinical samples correlates with higher expression of VEGF-A." (PMID 23185544, 2012). "The purpose of this study was to investigate whether TWIST1 expression predicts disease progression in a large breast cancer cohort with long-term clinical follow-up, and to reveal the biology related to TWIST1 mediated disease progression." (PMID 22967435, 2012). "The first seminal paper on TWIST1 in breast cancer also showed higher TWIST1 mRNA expression in infiltrative lobular carcinoma, which we also confirmed, though the implications of this remain unclear." (PMID 22967435, 2012). "However, all virgin WAP-Cre;K-rasG12D;Twist1 females developed multifocal breast carcinomas by 140 days of age, approximately 105 days after first transgene expression (p<0.001, median survival = 125 days, n = 9)." (PMID 22654675, 2012). "In this large retrospective study of 1,427 primary breast cancer patients, we determined whether the TWIST1 gene expression level is a prognostic marker." (PMID 22967435, 2012). "In breast cancer, Twist1 only partially induced an EMT program." (PMID 23133563, 2012). "First, can TWIST1 mRNA expression in breast cancer tissue predict disease progression?" (PMID 22967435, 2012). "Besides addressing the issue of where TWIST1 mRNA is predominantly expressed in breast cancer tissues we also performed IHC staining to ascertain the localization of TWIST1 protein." (PMID 22967435, 2012). "In order to investigate whether Twist1 was necessary for invadopodia, we generated knockdowns of Twist1 in 168FARN and 4T1 cell lines, two mouse mammary carcinoma cell lines that express high levels of Twist1." (PMID 21725138, 2011). "Combined inhibition of ARTN and PI3K/AKT/TWIST1 could therefore represent a valuable therapeutic approach in ER-MC mammary carcinoma." (PMID 22060274, 2011). "ARTN and TWIST1 may therefore functionally synergize in aspects of mammary carcinoma cell behavior other than EMT and metastasis reported herein." (PMID 22060274, 2011). "The prometastatic potential of TWIST1 in mammary carcinoma cells is well established." (PMID 22060274, 2011).
breast carcinoma (continued). "Of note, STAT3 transcriptionally upregulates TWIST1 expression and promotes breast carcinoma cell migration prompting speculation that STAT3-TWIST1 interactions in GBM may also contribute to invasion and mesenchymal change." (PMID 20646316, 2010). "Finally, we tested whether CXCL8 and CXCL1 expressions correlate with EMT-associated genes, including VIM (gene for Vim), SNAI1 (gene for Snail1), and TWIST1 (gene for Twist1) in breast cancer cell lines using the HMS LINCS dataset." (PMID 40833805, 2025). "Furthermore, TRIM29 plays a role in suppressing TWIST1 and the invasive behavior of breast cancer." (PMID 38444019, 2024). "Together, these results demonstrate that the FBXO3-USP4-Twist1 axis is critically important in p110αH1047R-induced cell migration and tumor metastasis, and that elevated expression of PIK3CA/FBXO3/USP4/Twist1 is associated with poor clinical outcomes of breast cancer patients." (PMID 38134227, 2023). "In breast cancer cells, mature adipocytes induce the EMT phenotype and promote cancer cell migration, invasion and proliferation, which could be associated with the upregulation of MMP-9 and twist-related protein 1 (TWIST1)." (PMID 36670988, 2023). "Additionally, in a case series of 100 early stage breast cancer, it was found that patients with EpCAM-enriched CTCs overexpressing TWIST1 and showing a stem cell profile, defined as CD44high/CD24−/low and ALDH1high/CD24−/low, had significantly reduced disease-free and overall survival." (PMID 36428760, 2022). "Furthermore, miR-381-3p could bind to the 3′-UTR of both Sox4 and Twist1, suggesting that miR-381-3p inhibits breast cancer EMT by targeting Sox4 and Twist1." (PMID 34362391, 2021). "Moreover, the authors also found that the metastasis rate of hypermethylated TWIST1 was higher in primary breast carcinomas, indicating that TWIST1 may be involved in EMT regulation through promoter hypermethylation." (PMID 34071109, 2021). "However, when Arg34 of Twist1 is mutated to lysine, no impact is observed on E-cadherin expression in A549 cells and even in breast cancer cell line MCF7." (PMID 33808323, 2021). "Studies using breast cancer cell lines have shown an important role of Twist1 in epithelial-to-mesenchymal transformation, intravasation and metastasis; more importantly, genetically ablating the Twist1 function effectively inhibited breast tumor cell intravasation and lung metastasis." (PMID 32655411, 2020). "In human mammary epithelial cells or breast cancer cells, EMT-associated transcription factors, including Snail1 and Twist1, could up-regulate this cytoskeletal structure, and vimentin filaments, a known marker for EMT, supported extension of these microtentacles." (PMID 32391382, 2020). "Therefore, we hypothesized that the potential regulatory mechanism of TFPI2 on breast cancer dependents on TWIST1." (PMID 32248791, 2020). "In addition, some studies point out that the up-regulation of EMT-associated transcriptional factors, containing Slug, Zeb1 and Twist1, can directly lead chemotherapy in breast cancer and NSCLC through the ATP-binding cassette (ABC) transporter family of proteins (ABCB1, ABCC1 and ABCG2)." (PMID 33282725, 2020). "Collectively, these results suggest that TBX3 may be facilitating the process of early invasion even at the earliest stages of progression (i.e. CCLs, DCIS), and offer potential roles for downstream EMT‐related proteins such as SLUG and TWIST1 in the invasiveness of early‐stage breast cancer." (PMID 30697731, 2019). "Moreover, IL-1β induces ICI-EMT in a 6D breast cancer cell model by activating the IL-1β/IL–1R1/β-catenin pathway and up-regulating Twist1, leading to ESR1 gene promoter methylation, and to methylation-dependent down-regulation of ERα receptor, linked to tamoxifen resistance." (PMID 31557902, 2019). "Thus, we could hypothesize that BTG2/TIS21-inhibited cancer invasion might be through the downregulation of Twist1 activity in human breast cancers." (PMID 31138781, 2019).
breast carcinoma (continued). "As previous reported, Src-1 could potentiate PEA3-mediated Twist1 expression in breast cancer." (PMID 30973923, 2019). "TNFα-mediated activation of canonical NF-κB signaling leads to the induction of multiple EMT-TFs, including Twist1, Snail, Snail2 (Slug), and Zeb1/2, and to the repression of E-cadherin expression, and NF-κB-dependent cell migration and invasion in breast cancer cells." (PMID 31557902, 2019). "Clinical data on the lncATB and Twist1 expression level revealed that higher expression level observed in triple-negative and Luminal B (Her-2 positive) breast cancer, relative lower level in Luminal A breast cancer, and the lowest level in normal mammary glands." (PMID 30518916, 2018). "To our knowledge, we are the first to show, using resources from a population-based follow-up study, that promoter methylation of APC, CCND2, HIN1, and TWIST1 may modify the inverse association between prediagnostic RPA and all-cause mortality following a breast cancer diagnosis." (PMID 28222775, 2017). "NCOA1 has previously been reported to be overexpressed in breast cancer and its increased expression positively correlated with disease recurrence and metastasis through working with multiple transcription factors to, in turn, upregulate the expression of Twist1, ITGA5, CSF-1, SDF1 and CXCR4." (PMID 28060733, 2017). "Moreover, TWIST1 is a transcriptional repressor of E-cadherin gene expression in breast cancer." (PMID 27930738, 2016). "However, no clear association was found between TWIST1 promoter methylation and TWIST1 expression in breast cancer." (PMID 26023736, 2015). "Furthermore, Activation of AKT and TWIST1 in mammary carcinoma cells has previously been described." (PMID 22060274, 2011). "Thus, even though TWIST1 expression is not repressed by methylation, the compelling association between TWIST1 CpG methylation and malignancy makes it a useful biomarker for breast cancer diagnosis and prognosis." (PMID 19995452, 2009). "Its increased expression improves progression-free survival in breast cancer and can inhibit carcinogenesis in HCC by targeting Twist1." (PMID 41226545, 2025). "The transcription factors like TWIST1 and SNAI1 facilitate the metastasis of breast cancer to other vital organs." (PMID 41321380, 2025). "A study in breast cancer stem cells reported a similar correlation, wherein SATB1 led to the upregulation of Snail1 and Twist1 through the activation of Notch signaling." (PMID 40689929, 2025). "In the context of basal-like breast cancer (BLBC), the abnormal presence of Twist1 induces EMT and properties akin to cancer stem cells, simultaneously suppressing ERα expression to enhance the resistance of breast cancer cells to chemotherapy drugs." (PMID 40003882, 2025). "Garcinol has been reported to inhibit NF-κB/Twist1 signaling activated by paclitaxel and downregulate the expression level of EMT-TFs, thus significantly improving the efficacy of paclitaxel in breast cancer in the orthotopic breast cancer model." (PMID 41211430, 2025). "Our finding of the enrichment of H3K36me3 mark near the HREs of TWIST1 and SNAIL1 promoters is in interesting parallel to the increase of H3K36me3 mark at the HRE region of PDK1 gene in breast cancer cell line SUM159 upon hypoxia treatment." (PMID 40764968, 2025). "Initially, we used RNA to determine the expression levels of NF-κB, TWIST1, SIP1, and SLUG in two breast cancer (BC) cell lines, HCC-1954 and MDA-MB-231, classified as HER2+ and triple-negative breast cancer (TNBC) subtypes, respectively." (PMID 41285837, 2025). "Studies have shown that SLUG increases cytoplasmic β-catenin stability by inducing certain inflammatory factors such as IL-8 and TNF-α, while TWIST1 regulates CD24 expression, promoting stem cell characteristics in breast cancer." (PMID 39858015, 2025).
breast carcinoma (continued). "The presence of miR-186-5p has been linked to drug resistance in treatments such as cisplatin, methotrexate, and taxol by targeting twist-related protein-1 (TWIST-1), a major EMT-related transcription factor in breast cancer and gastric cancer." (PMID 40149313, 2025). "These include EMT (TWIST1, SNAIL1, RUNX1, RUNX2, HIF1, and NOTCH1), breast cancer maintenance (OCT4, SP1, GATA1, ATF1, FOXO3a, ELK1, VDR, and NRF1), pro-metastatic responses (SMAD2/3, HNF1a, GLI1, NANOG, YY1, MYB1, and AP1), and immune modulation (STAT1/3)." (PMID 38398186, 2024). "However, the relationship between TWIST1 and PD-L1 or immune evasion in breast cancer is unknown." (PMID 38893094, 2024). "The BRD4 protein (bromodomain-containing protein 4) regulates chromatin structure, and interactions between TWIST1 and BRD4 contribute to tumorigenesis in breast cancer." (PMID 38935814, 2024). "In this study, we found that the expression levels of TWIST1 and its direct target genes as well as PD-L1 are the highest in ER−/HER2− breast cancers." (PMID 38893094, 2024). "Further experimental validation confirmed that enhanced Twist1 and Slug transcription factors regulate EMT and facilitate tumor cell migration and invasion after H2A.X deletion in breast cancer." (PMID 39199381, 2024). "The expression of commonly studied EMT markers (SLUG, SNAIL, TWIST1, ZEB1) correlated well with the poor prognosis in breast cancer patients." (PMID 37975220, 2024). "Collectively, these results suggest that the expression levels of TWIST1 and CD274 (PD-L1) are positively correlated in ER−/HER2−/TWIST1+ breast cancer cells, including the TWIST1-reprogrammed MCF7-TWIST1 cell lines." (PMID 38893094, 2024). "Among five subtypes of human breast tumors, the expression levels of TWIST1 and its upregulated genes, Vim and SNAI2, are the highest, while its repressed target genes, CDH2 and ESR1, are the lowest in ER−/HER2− breast cancers." (PMID 38893094, 2024). "The knockdown of TWIST1 or BRD8 largely diminished PD-L1 expression and enhanced the CD8+ T-cell-mediated inhibition of breast cancer cell growth." (PMID 38893094, 2024). "In metastatic breast cancer cells, the EMT master TF Twist1 binds the promoter of miR-10b, which has been classified as a metastamir, increasing miR-10b gene expression and consequently stimulating both cell migration and invasion." (PMID 38473317, 2024). "Increases Twist1 and Slug transcription factors, regulates EMT, and facilitates tumor cell migration and invasion after H2A.X deletion in breast cancer." (PMID 39199381, 2024). "Additionally, the levels of the SLUG gene remained unchanged while the TWIST1 gene was upregulated following exposure of the cancer cells to bacteria, indicating that P. acidilactici may promote epithelial-mesenchymal transition in breast cancer." (PMID 38314029, 2024). "It has been shown that co-culturing mature adipocytes with breast cancer (BC) cells enhances cancer cell growth and EMT by increasing the expression of FOXC2, TWIST1, and N-cadherin." (PMID 39201656, 2024). "High ECM stiffness upregulates TWIST1, which promotes epithelial-mesenchymal transition (EMT) and the metastasis of breast cancer cells." (PMID 37864030, 2023). "A recent study reveals that Twist1 regulates EPHA2 expression thereby influencing tumor growth and metastasis in basal-like breast cancer." (PMID 38008720, 2023). "The multifocal breast carcinomas developing in WAP-Cre; K-rasG12D; Twist1 transgenic females exhibit features of mesenchymal transdifferentiation and gene expression profiles associated with the claudin-low subtype." (PMID 37176013, 2023). "Here, we investigated a potential physical/functional interaction between Twist1 and USP13 in human breast cancer." (PMID 36732432, 2023). "In breast cancer, elevated substrate rigidity (from 150 Pa to 5700 Pa) facilitates EMT and cancer cell invasion via TWIST1–G3BP2 and EPHA2/LYN/TWIST1 pathways." (PMID 37864030, 2023).